NLRP3 (NLR family pyrin domain containing 3)
Diseases named in the same sentence as NLRP3 in open-access papers (continued):
Sharing a sentence is not in itself a finding about the gene and the disease.
psoriasis (continued). "These lines of evidence led us to hypothesize that metformin treatment may modulate mature IL-1β secretion via NLRP3 inflammasome in the skin, resulting in the prevention of psoriasis development." (PMID 32194991, 2020). "NLRP3 rs10733113 and CARD8 rs2043211 were found to increase the risk of psoriasis in a Swedish population, supporting the hypothesis that inflammasome variation predisposes individuals to psoriasis." (PMID 32528469, 2020). "The NLRP3 inflammasome is closely related to the mechanism of psoriasis." (PMID 32104685, 2020). "To address whether LPA5 could influence psoriasis-induced NLRP3 expression in macrophages, we performed double immunofluorescence for NLRP3 and F4/80 in IMQ-applied mouse skin." (PMID 32707926, 2020). "To address whether LPA5 could influence NLRP3 inflammasome activation in psoriasis lesion, we determined NLRP3 expression levels through immunofluorescence." (PMID 32707926, 2020). "However, Cho found that the NLRP3 inflammasome can be activated in IMQ-treated caspase-1-deficient mice, although the severity of psoriasis was much lower than in wild-type mice." (PMID 32528469, 2020). "In order to verify a possible role of TTP and NLRP3 inflammasome pathway in psoriasis, we initially observed if any variation affecting their mRNAs expression could be detected in psoriatic skin samples." (PMID 33585499, 2020). "BAY 11-7082 alleviates the dual NF-κB and NLRP3 inhibition-dependent psoriasis-like dermatitis." (PMID 32528469, 2020). "Notably, TCLPA5 administration attenuated the upregulation of macrophage NLRP3 in injured skin of mice with imiquimod-induced psoriasis." (PMID 32707926, 2020). "Here, the activated NLRP3 inflammasome as an upstream trigger could govern the pathogenesis of tissular inflammatory injuries in psoriasis." (PMID 31181689, 2019). "The immunohistochemical results showed that the NLRP3 inflammasome signals were observed to be significantly increased in the psoriasis mice; furthermore, the expressions of NLRP3, ASC, caspase-1, and IL-1β were upregulated, which were all inhibited through EPD treatment." (PMID 31181689, 2019). "Hence, this research was aimed at further proving and evaluating the anti-psoriasis effect of Flos daturae as well as exploring the roles of the TLR7/8–MyD88–NF-κB and NLRP3 pathways in its underlying mechanisms." (PMID 31181689, 2019). "Therefore, genome editing of the NLRP3 inflammasome could alleviate the inflammatory symptoms of psoriasis." (PMID 40006568, 2025). "Research has shown that NLRP3 may be a promising therapeutic target for the treatment of psoriasis." (PMID 39148738, 2024). "Importantly, NLRP3 is highly expressed in psoriasis samples and the blockers of NLRP3 pathway may be recognized as novel therapeutic targets of psoriasis through ameliorating inflammatory reaction during the disease course." (PMID 38967379, 2024). "Besides, whether the mechanism of THL involved in the regulation of psoriasis is mainly mediating the deubiquitination of NLRP3 as previously discussed awaits further validation by subsequent experiments." (PMID 37506136, 2023). "Therefore, NLRP3 has the potential to become a novel target when treating psoriasis." (PMID 37686332, 2023). "Modulating the expression of NLRP3 inflammasome by MAEO suggests that inhibiting its activity could be a potential therapeutic strategy for treating inflammatory skin disorders such as psoriasis and eczema." (PMID 37175425, 2023). "Polymorphisms in NLRP3 and CARD8 are associated with increased risk of psoriasis development, while NLRP1 mutations have been associated with diverse cutaneous inflammatory diseases, including psoriasis, highlighting the critical role of NLRP1 in epidermal biology." (PMID 35929827, 2022).
psoriasis (continued). "Although literature data suggest that activated monocytes from psoriasis patients show significantly higher NLRP3 activity than healthy controls and that also contributes to the disease pathology, we could not detect differences in NLRP3 activity between the two groups." (PMID 36293012, 2022). "Thus, therapies targeting the NLRP3 inflammasome pathways may have significant potential in the management of fatigue and improvement in the quality of life in patients living with psoriasis." (PMID 35663672, 2022). "Moreover, LPAR5 is involved in NLRP3 inflammasome activation in macrophages of psoriatic lesions and also keratinocyte activation to produce inflammatory cytokines, contributing to psoriasis pathogenesis." (PMID 34639115, 2021). "Moreover, some plants, including Datura Metel L. mustard seed and rosmarinic acid (RA), play a protective role against the development of imiquimod-induced psoriasis by inhibiting NLRP3 inflammasome activation by cytokines, such as IL-1β, IL-6, IL-8, CCL20, and TNF suppression." (PMID 34072753, 2021). "However, NLRP3 knockout only partly reduced psoriasis-like dermatitis in mice." (PMID 33912556, 2021). "To address how LPA5 signaling might contribute to skin injury in psoriasis, we determined its role in macrophages, particularly in their NLRP3 inflammasome activation using in vivo psoriasis mice and in vitro lipopolysaccharide (LPS)-primed bone marrow-derived macrophages (BMDMs)." (PMID 32707926, 2020). "In an rIL-23-induced psoriasis mouse model, a TLR-7,−8, and−9 antagonist inhibited the dermal expression of Nlrp3 and Aim2 and reduced the secretion of Th1 and Th17 cytokines in skin and serum, suggesting that inflammasomes might be a therapeutic target for psoriasis treatment." (PMID 32528469, 2020). "This NLRP3-relevant mechanistic notion could be supported by previous reports showing that NLRP3 expression is upregulated in human psoriasis biopsy and that genetic deletion of NLRP3 can significantly ameliorate skin thickening in mice with IMQ-induced psoriasis." (PMID 32707926, 2020). "Thus, the targeted inhibition of the NLRP3 pathway, and subsequent reducing inflammatory injury might be an effective method of psoriasis treatment." (PMID 31181689, 2019). "Therefore, NLRP1 and NLRP3 may play roles in the dysregulated innate immune response that is characteristic of psoriasis." (PMID 29850521, 2018). "Development of psoriasis via IL-23 is dependent on P2X7 receptor signaling and subsequent activation of NOD-like receptor P3 (NLRP3) in cutaneous myeloid dendritic cells." (PMID 40678003, 2025). "One study revealed that inflammasome sensors, NLRP3, NLRP1, CASP1, and AIM2, enhanced expression in psoriasis patients." (PMID 36110207, 2022). "The databases were searched using the terms “inflammasome”, “NLRP1”, “NLRP3” or “AIM2” and “psoriasis” or “psoriatic arthritis”." (PMID 34072753, 2021). "We observed significantly higher expression of NLRP3 in early CTCL than in CS and psoriasis as a BID." (PMID 34220814, 2021). "In this systemic review, we collect recent and comprehensive evidence from the inflammasomes, NLRP1, NLRP3, and AIM2, in pathogenesis of psoriasis." (PMID 34072753, 2021). "In psoriasis mouse models induced by imiquimod, the expression of TLR7, TLR8, p-NF-κB, and NLRP3 were obviously suppressed by administration of Datura metel L." (PMID 34707607, 2021). "In this review, from the perspective of activators and inhibitors, we collected evidence from the widely-studied inflammasomes, NLRP3, AIM2, and NLRP1, in psoriasis, vitiligo, SLE, and AD." (PMID 32528469, 2020). "Accordingly, the pathogenesis and progress of psoriasis were closely related to TLR7/8-MyD88-NF-κB and NLRP3 pathways." (PMID 31181689, 2019). "Validation through clinical psoriasis patient samples revealed that, compared to non-lesional tissue, the expression levels of IL-1β and NLRP3 were remarkably upregulated in lesional tissue." (PMID 41383588, 2025).
psoriasis (continued). "The gene expression of these key members (Caspase-1, Nlrp3, Gsdmd, Il-1β) was significantly increased in the lesions of psoriasis (P < 0.01) compared with nonlesional skin." (PMID 38125299, 2024). "The association of NLRP3 (rs10754558) gene polymorphism, TNFα and CRP with disease severity and their role as biomarkers for response to different systemic therapy in psoriasis have not been explored to date." (PMID 38965465, 2024). "Patients with psoriasis present relatively high plasma levels of inflammasome-generated IL-1β and high expression of inflammasome components such as NLRP3, NLRP1, and absent in melanoma 2 (AIM2)." (PMID 37964882, 2023). "Growing evidence also demonstrates the role of the NLRP3 inflammasome and its pro-inflammatory cytokines (e.g., IL-1β and tumor necrosis factor (TNF)-alpha) in patients with psoriasis, suggesting the potential of inhibiting NLRP3 and its cytokines in managing psoriasis and fatigue." (PMID 35663672, 2022). "In addition, we found higher NLRP3, ASC, caspase-1 and IL1B mRNA levels in PBMCs from psoriasis patients compared with healthy individuals." (PMID 36293012, 2022). "Reaffirming the role of inflammasomes as a potential therapeutic target in the treatment of psoriasis, as with the NLRP3 inflammasome, researchers focused on finding substances that would silence or completely inhibit AIM-2 inflammasome activation in psoriasis." (PMID 34072753, 2021). "However, the protective role and decrease of NLRP3 inflammasome have also been detected in T1D, IBD, SLE, and psoriasis." (PMID 34707607, 2021). "TTP can directly target the degradation of NLRP3 mRNA; therefore, TTP downregulation may contribute to pathogenesis of psoriasis via NLRP3 inflammasome activation." (PMID 34707607, 2021). "In contrast, in a murine model of psoriasis the inflammasome pathway has only an effect upon ablation in immune cells, but not in keratinocytes, and the targeting of NLRP3 ameliorates imiquimod-induced psoriasis." (PMID 32053878, 2020). "More importantly, our in vivo studies demonstrated that amounts of LPA species in psoriasis lesions were elevated and that suppressing LPA5 activity could attenuate NLRP3 upregulation in psoriasis lesions, particularly in infiltrated macrophages." (PMID 32707926, 2020). "Given data showing that amounts of LPA species were elevated in psoriasis lesions, we first determined whether LPA could increase NLRP3 expression in LPS-primed BMDMs." (PMID 32707926, 2020). "Although metformin reportedly inhibits mature IL-1β secretion via NLRP3 inflammasome in macrophages of T2DM patients, it remains unclear whether it affects skin inflammation in psoriasis." (PMID 32194991, 2020). "Based on our results; AIM2 and IFI16 are highly expressed inflammasome receptors in psoriasis, whereas NLRP3 was not among the DEGs." (PMID 26976200, 2016). "Notably, genes such as Nlrp3, Casp1, Casp4, IL-1β, IL-18, and Stat1 had high degree values, indicative of their significant position in the PPI network and potential targets for FZHFZY treatment of psoriasis." (PMID 41383588, 2025). "In vitro studies also exhibited that LPA could activate LPS-induced nucleotide-binding oligomerization domain-like receptor family pyrin-domain-containing 3 (NLRP3) inflammasome via LPA5, and LPA5 signaling was found to upregulate the NLRP3 expression in psoriasis lesions." (PMID 37569902, 2023). "Thus, further investigation on regulating NLRP3 inflammasome of keratinocyte activation and developing a novel strategy for fighting psoriasis are needed." (PMID 37686332, 2023). "Furthermore, in contrast to pDCs, monocytes from psoriasis patients do not show a reduced NLRP3 activity in response to the same activation signals." (PMID 36293012, 2022).
psoriasis (continued). "Finally, we also compared the expression of NLRP3 pathway components in the CD14+ monocyte population from psoriatic and healthy individuals, since inflammatory cytokines produced in excess by circulating monocytes also play an important pathological role in psoriasis." (PMID 36293012, 2022). "Moreover,skin-specific NLRP3 suppression can inhibit the proliferation and chemotaxis ofkeratinocytes through the downregulation of IL-1β, IL-23, IL-17A, C-X-Cmotif chemokine ligand 1 (CXCL1), as well as the improvement of Treg/Th17 ratio,thus ameliorating the skin lesions induced by psoriasis." (PMID 39076663, 2022). "TCLPA5 administration-attenuated immunoreactivities of both F4/80 and NLRP3, along with LPA5 upregulation in infiltrated macrophages, collectively suggest that LPA5 could regulate NLRP3 inflammasome activation in macrophage to induce inflammatory responses in psoriasis." (PMID 32707926, 2020). "Our study indicated that EPD could alleviate psoriasis in the IMQ-induced mice model and that the potential mechanisms that were involved were, at least in part, due to inhibiting the inflammation responses via the TLR7/8–MyD88–NF-κb–NLRP3 inflammasome signaling pathway." (PMID 31181689, 2019). "Several types of inflammasomes are recognized, including NLRP1, NLRP3, and absent in melanoma 2 (AIM2), in the pathogenesis of psoriasis." (PMID 35663672, 2022). "In contrast, methotrexate, a folate antagonist used for the treatment of severe inflammatory conditions, including psoriasis, did not reduce caspase-1 activity in psoriasis patients, suggesting that TNF-α inhibition is superior in reducing NLRP3-dependent inflammation during psoriasis." (PMID 37443800, 2023). "Furthermore, mRNA of NLRP1, NLRP3, AIM2, PYCARD and CASP1 was observed in both lesional and non-lesional epidermis of psoriasis patients." (PMID 37325658, 2023).
systemic lupus erythematosus (93 papers, 2013 to 2025). An autoimmune multi-organ disease typically associated with vasculopathy and autoantibody production. "Conversely, forced overexpression of NLRP3 exacerbates end-organ damage in lupus mice, underscoring its pathogenic role in LN progression." (PMID 41357229, 2025). "Proteins from previous studies that associated with lupus such as NLRP3, CD171, and others were also examined." (PMID 38524134, 2024). "A gain-of-function mutation of NLRP3 in pristine-induced lupus mice exhibited high mortality, high levels of proteinuria, and severe pathologic changes in the kidney." (PMID 31694192, 2019). "In contrast with the concept of a critical role for inflammasome activation in autoimmunity, inflammasome deficiency due to a point mutation in the NLRP3 gene has recently been identified in lupus-prone NZB/W F1 mice correlating with reduced IL-1β release." (PMID 26579125, 2015). "NLRP3 inflammasome has been implicated in the pathogenesis of systemic lupus erythematosus (SLE)." (PMID 27250627, 2016). "In lupus model mice, activation of the NLRP3 inflammasome was observed in podocytes, leading to renal tissue damage, podocyte foot process disruption, and the manifestation of proteinuria." (PMID 41357229, 2025). "Animal experiments have shown that baicalin can improve renal function and pathological manifestations in lupus model mice by downregulating the activation of NLRP3 inflammasomes and the phosphorylation level of NF-κB." (PMID 40585331, 2025). "The inhibitor of the serine/threonine kinase Pim-1 “SGI-1776” was identified as a promising therapy, corroborating experimental data which suggest that inhibition of the Pim-1/NFATc1/NLRP3 pathway ameliorates nephritis in lupus mouse models." (PMID 37072752, 2023). "In mice, the overexpression of TNFAIP3 inhibits NLRP3 inflammasome complex, preventing lupus inflammation and renal injury." (PMID 37252693, 2023). "Anti-double-stranded DNA antibodies, the hallmark antibody of systemic lupus erythematosus (SLE), have been found to bind to TLR4, which in turn activates NLRP3 inflammasome." (PMID 37386410, 2023). "Metabolic regulation has been shown to be effective in a lupus mouse model and PBMCs from lupus patients to alleviate symptoms through an mTOR and NLRP3 regulation effect." (PMID 36743677, 2022). "Several studies have also indicated that NETs-mediate the activation of the NLRP3 inflammasome in macrophages of lupus patients, subsequently promoting IL-1β production via ROS and K+ efflux." (PMID 35958572, 2022). "Studies have also determined the activation of the podocyte NLRP3 inflammasome in both lupus-prone mice and LN patients." (PMID 35958572, 2022). "Mouse studies of lupus nephritis, the manifestation of lupus in kidneys, also indicates NLRP3 activation." (PMID 34202842, 2021). "NLRP3 activation has been identified in lupus by measuring patients’ peripheral blood mononuclear cells." (PMID 34202842, 2021). "The NLRP3 inflammasome activated in glomerular podocytes results in severe proteinuria in mouse lupus models and in patients with LN." (PMID 34489689, 2021). "NLRP3 gene expression was significantly increased concomitant to the progression of lupus nephritis in an MRL/lpr lupus model." (PMID 33534121, 2021). "In MRL/lpr mice, a spontaneous lupus model, the expression of NLRP3, ASC, and active caspase l-p20 subunit protein was upregulated in the kidney, compared with control mice." (PMID 34489689, 2021). "Iron can directly activate the NLRP3 inflammasome in monocytes, and the NLRP3 inflammasome is activated in podocytes from lupus-prone mice and from LN patients." (PMID 33912577, 2021). "In addition, the immune complexes in systemic lupus erythematosus (SLE) patients can trigger the NLRP3 inflammasome, activate macrophages, and cause cell and tissue damage." (PMID 32148650, 2020).